GDF15 (growth differentiation factor 15)
Diseases named in the same sentence as GDF15 in open-access papers (continued):
Sharing a sentence is not in itself a finding about the gene and the disease.
tumor (continued). "In light of the findings that the overall predictive value was reversed in the presence of certain immune cell content, we suggested that enriched Th1, enriched Treg, enriched eosinophils, and decreased NKTs may be counteracting factors on the tumor-regulatory role of miR-216a and GDF15." (PMID 34948431, 2021). "Furthermore, GDF15′s tumor promoting role in COAD has been noted in several reports." (PMID 34948431, 2021). "Moreover, GDF-15 can be directly regulated by sex hormones in some tumor cells, which indicates that there might be a relationship between serum sex hormone levels and GDF-15 levels." (PMID 34942914, 2021). "Since the activation of degradation pathways were only present in GDF15-KD stroma, this might indicate that these cells were undergoing a process of apoptosis, which could explain the decrease in the stromal composition in GDF15-KD tumor." (PMID 33086658, 2020). "However, the effects of GDF15 on tumor development are not well understood and are contradictory." (PMID 33062674, 2020). "Thus, a role for GDF-15 in tumor immune escape is supported by many studies." (PMID 32508832, 2020). "However, the exact role of GDF15 in tumor progression still needs to be well elucidated." (PMID 32076610, 2020). "Thus, GDF-15 may promote immune escape of tumor cells by inhibiting T cell stimulation and cytotoxic T lymphocyte activation by dendritic cells." (PMID 32508832, 2020). "While in the GDF15-KD stroma, various degradation pathways were activated, including the degradation of melatonin, serotonin, ethanol, nicotine, acetone, and bupropion, which might play a role in chemosensitivity of this tumor." (PMID 33086658, 2020). "Linking to the critical role of fatty acid oxidation in metastasis of tumor cells, we hypothesize that the exacerbated GDF15 regulates the EMT and metastasis of CRC cells via enhancing the utilization of fatty acids to produce more fuels for cell growth and migration." (PMID 32076610, 2020). "Still, it should be explored whether such tumor-suppressive effects can be explained by GDF-15 inhibiting tumor-promoting inflammation, which would be in line with the known functions of GDF-15 and help to provide a conceptual understanding for risk assessment." (PMID 32508832, 2020). "In addition to proliferation, GDF-15 also induces angiogenesis in advanced tumor processes." (PMID 29467963, 2018). "GDF-15 may interfere with the recruitment of monocytes and neutrophils into the tumor niche." (PMID 29467963, 2018). "Pro-angiogenesis could be another way for GDF-15 to promote tumor growth." (PMID 28489602, 2017). "Therefore, GDF-15 seems to be involved in regulating tumor cell growth." (PMID 28489602, 2017). "In addition, GDF15 might contribute to tumor progression through paracrine manners, because the exogenous rhGDF15 also could enhance the potential of metastasis in CRC." (PMID 26497212, 2016). "As same as TGF-β, GDF15 may also act as a double-edge sword during the tumor development process." (PMID 26497212, 2016). "Thus, higher GDF15 levels in A2780cis tumors might decelerate tumor growth and therefore decrease the accessibility to replicating DNA for platinum compounds." (PMID 25490861, 2015). "Thus, GDF-15 may be one of the critical molecules involved in tumor immune escape and may be a novel target in tumor immunotherapy." (PMID 24236027, 2013). "This may be a possible mechanism in vivo that GDF-15 could interfere with migration of DCs from the site of tumor to draining LNs, leading to less tumor immunity, inhibiting the ability of DCs to activate the tumor-specific immune response in vivo." (PMID 24236027, 2013).
tumor (continued). "Compared with the mDC group, GDF-15 could accelerate the tumor growth rate and increase tumor size." (PMID 24236027, 2013). "NF-κB alters the tumor microenvironment by modulating the secretion of cytokines and chemokines (GDF15, CCL3, and CCL4), promoting tumor cell survival and drug resistance." (PMID 40760228, 2025). "Accumulating evidence indicates that GDF15 expression is elevated in GBM and correlates with tumor progression and an immunosuppressive microenvironment 30-32." (PMID 41281763, 2025). "Our study especially underscores the potential application of GDF15 in HNSCC, particularly its regulatory role in oxidative stress within tumor cells." (PMID 41035818, 2025). "In this context, emerging candidates such as GDF-15, VEGF, TGF-β1, HSP90, HMGB1, and S100A9 have garnered considerable attention for their roles in tumor progression, angiogenesis, immune modulation, and stress response." (PMID 41009692, 2025). "Using RT-qPCR analysis, the expression levels of DJ-1, GDF15, and MFGE8 genes were evaluated according to sex, tumour grade, tumour diameter, and Ki-67 Pi." (PMID 41009755, 2025). "GDF15 is expressed by various cell types in the liver and HCC tissues, including hepatic stellate cells, macrophages, tumor cells, and hepatocytes." (PMID 40677718, 2025). "Elevated circulating levels of GDF15 have been shown to contribute to weight loss, muscle wasting, and impaired tolerance to treatment, all of which may negatively affect overall survival, independent of tumor burden." (PMID 40725563, 2025). "In our research, GDF15 was involved in the recruitment and switch of myCAFs, which reinforces the immuno‐isolation microenvironment around MP7 state tumour cells, providing a new perspective on the obstruction of T cell infiltration mediated by GDF15." (PMID 40292733, 2025). "Growth differentiation factor 15 (GDF15), a cytokine elevated in HCC patients following DAA treatment, promotes immunosuppression in the tumor microenvironment." (PMID 40060195, 2025). "Further research is warranted to clarify aberrant GFRAL expression in tumour tissues and the immunomodulatory effects of the GFRAL antagonists via neural pathways and direct effects on tumour cells, compared to anti-GDF-15 treatment." (PMID 41294666, 2025). "Next, according to the expression level of GDF15, we divided HNSCC tumor cells into high GDF15 tumor cells and low GDF15 tumor cells." (PMID 41035818, 2025). "Together, these results suggested that GDF15 promoted neutrophil recruitment and activation through a TNF-α-dependent paracrine loop, ultimately promoting tumor progression." (PMID 41035818, 2025). "Growth differentiation factor-15 (GDF-15) represents another, largely hepatocyte- and tumor cell-expressed cytokine that is increased in MASLD and suppresses antitumor immunity." (PMID 40595432, 2025). "GDF15 promotes radioresistance through multiple mechanisms, including inhibition of ferroptosis via NRF2 stabilization and modulation of the tumor immune microenvironment." (PMID 41281763, 2025). "GDF15 (P = 1.62E‐12), GDF11 (P = 1.38E‐2), GDF9 (P = 7.2811E‐3), and GDF3 (P = 4.95E‐6) were significantly up-regulated in primary tumor tissue (n = 415) compared with that in normal tissue (n = 34)." (PMID 40153751, 2025). "In conclusion, our study shows that NAG-1/GDF15, via its full-length pro-NAG-1/GDF15 form, functions intracellularly as a tumor suppressor by inhibiting the oncogenic protein EpCAM, which in turn reduces β-catenin and NF-κB signaling." (PMID 40316530, 2025). "We discuss GDF15’s roles in metabolic stress and immune regulation, VEGF’s central role in neovascularization, and TGF-β1’s dualistic tumor-suppressive and promotive effects." (PMID 41009692, 2025).
tumor (continued). "By specifically knocking out the immunosuppressive molecule GDF15 in HCC cells in mice, we reversed the tumor immunosuppressive microenvironment and promoted immune cell killing of tumor cells." (PMID 38704691, 2024). "The mRNA levels of the cytokines CCL5, CCL18, and GDF15, as well as the transcription factor IRF4, correlated weakly positively with the tumor volume." (PMID 39272860, 2024). "The expression of secreted protein‐coding genes, including MDK, HGF, RARRES2, GDF15, IL6 and MIA, was concentrated in the tumour cell‐enriched region, thus confirming the expression specificity of these signalling molecules." (PMID 38318640, 2024). "This increased ECM circulation can produce cytokines, including growth differentiation factor 15 (GDF15) and TGF-β, which enhance tumor cell proliferation and invasion." (PMID 39092186, 2024). "Accordingly, TGF-β and GDF15, a member of the TGF‐β superfamily, play a key role in tumor invasion and EMT, which is considered an essential mechanism in TGF-β-induced tumor invasion." (PMID 39003350, 2024). "The mRNA levels of the cytokines CCL5, CCL18, and GDF15, as well as the transcription factor IRF4, showed a positive correlation with the tumor volume." (PMID 39272860, 2024). "M2 TAMs release growth differentiation factor 15 (GDF15), a member of the transforming growth factor beta (TGF-β) family, to stimulate fatty acid oxidation in tumor cells." (PMID 38794298, 2024). "Hyperactive signals sent primarily by tumour cells were identified, such as MDK, HGF, chemerin, and GDF15 signalling." (PMID 38318640, 2024). "The intercellular communication network in CM was found to be orchestrated primarily by tumour cells, and hyperactive signals sent primarily by tumour cells were identified, such as MDK, HGF, chemerin and GDF15 signalling." (PMID 38318640, 2024). "In PPIB-injected mice subcutaneous tumor tissues, the elevated ratio of TUNEL-positive cells was witnessed, and increased expressions of GDF15 were probed." (PMID 38360722, 2024). "BMP4, GDF15 and ACVR1B were expressed at higher levels in HER2 positive tumours which were correlated with poorer OS." (PMID 37333824, 2023). "The intersection set analysis of the bioinformatics database and transcriptome array data identified six common genes, FSTL1, GDF15, IQSEC2, KDM3A, LTC4S and TCTEX1D4, in which most of them were involved in tumor cell proliferation and growth." (PMID 38201443, 2023). "These genes were FSTL1, GDF15, IQSEC2, KDM3A, LTC4S and TCTEX1D4, in which most of them were involved in tumor cell proliferation and growth." (PMID 38201443, 2023). "We also investigated an external patient cohort consisting of 28 normal prostate samples, 98 primary tumours, and 13 bone metastases to investigate the levels of GFRAL, the receptor for GDF-15, in prostate tissues." (PMID 37781173, 2023). "Anti-GDF-15 treatment indeed enhanced the trafficking of CD4+ and CD8+ T cells to tumor-draining lymph nodes." (PMID 37474523, 2023). "While GDF-15 is highly overexpressed in about 50% of solid human tumors, elevated GDF-15 levels are rare in murine tumor cell lines." (PMID 37474523, 2023). "BMP4, GDF15 and ACVR1B were positively correlated with both ER and HER2 in Luminal B (ER+, HER2+) tumours." (PMID 37333824, 2023). "Altogether, seven factors were detected both in MC38-conditioned media and MC38 tumor-bearing serum: CCL2, GDF-15, Proliferin, CXCL10, Osteopontin, PCSK9 and Serpin E1." (PMID 35962398, 2022). "Together, TGF-β and its super family-like GDF15 play a pivotal role in tumor invasion, and the EMT is regarded as an important mechanism in TGF-β induced tumor invasion." (PMID 35327584, 2022). "Results of western blot suggested that GDF-15 was enriched in exosomes compared to the 10 K pellet and secretomes, indicating that GDF-15 was secreted from tumor cells mainly through exosomes." (PMID 35379793, 2022).
tumor (continued). "GDF-15 is a member of the transforming growth factor-β (TGF-β) superfamily, which plays an important role as an inflammatory marker in tumor pathogenesis, and ischemic, and metabolic diseases." (PMID 36698935, 2022). "Interference of GDF15 (siRNA or N70Q dominant negative) or EGFR pathway (inhibitor or siRNA for EGFR, SRC or ERK) decreases the resistant-cell survival in culture and tumor growth in mice." (PMID 35853851, 2022). "Taken together, GDF-15 is proposed as a novel tool to diagnose PCa vs. BPH or malignancy (GS6 vs. higher GS) and as a potential target for anti-tumor therapy." (PMID 36230513, 2022). "The expression levels of ALOX12B, GPX2, DDIT4, GDF15, and RRM2 in tumor tissues were significantly higher than those in the normal lung tissues." (PMID 34307361, 2021). "For instance, the expression of the ciliated epithelial markers, including FOXJ1, PIGR, CAPS, and GDF15, declined during the process of metastasis, although they were overexpressed in EC2 that mainly consisted of primary tumor cells." (PMID 34459128, 2021). "APC patients with high serum GDF-15 levels also had high serum CA19-9 levels, suggesting high tumor burden." (PMID 34638326, 2021). "For example, GDF15, namely a divergent TGF-beta superfamily cytokine, slowed the growth of PCa by irritating tumor immunity." (PMID 33995646, 2021). "In macrophages or tumor cells, the transcription factor STAT6 or NF-kB is reported to be involved in inducing GDF15 expression." (PMID 34877504, 2021). "The results showed that the expression of HAMP, FDFT1, GDF15, TFAP2C all increased in tumor tissues, indicating their meaningful regulatory roles in CRC." (PMID 34249766, 2021). "Among them, DDIT4 and HNF4A were highly expressed in tumor tissues, whereas ALOX15, IL33, and GDF15 were lowly expressed." (PMID 34434660, 2021). "APC patients with high serum GDF-15 showed signatures of cachexia and activation of the signaling pathways involving Akt and JNK in the tumor." (PMID 34638326, 2021). "In the same vein, GDF-15, in combination with BMP-2, has been shown to mediate the inhibition of fenretidine-dependent tumor vessel growth by interfering with endothelial cell growth, migration, and invasion." (PMID 33790859, 2021). "Highly expressed GDF15 promotes the metastasis of CRC cells and meanwhile accelerates the growth of tumor cells." (PMID 32076610, 2020). "In MSC-CA and MSC-DCIS, here we determined the decreased expression of GDF15 and IGF, but this conflicts with published results which show increased expression of these genes in the tumor micro-environment." (PMID 32093026, 2020). "Our studies found that up-regulation of GDF15 expression in HUVECs was accompanied by increased expression of POSTN, indicating that GDF15 secreted by tumor cells modulates POSTN levels in the extracellular matrix." (PMID 33193874, 2020). "The results of IHC staining exhibited that GDF15 levels of tumors were much higher than that of peritumor, and moreover, CHOP levels also significantly increased in tumor tissues, suggesting the positive correlation between GDF15 and CHOP." (PMID 32076610, 2020). "The indirect pathway, mediated by visfatin-primed ADSCs, promoted tumor stemness and EMT through a GDF15-pAKT pathway." (PMID 31861872, 2019). "Growth differentiation factor 15 (GDF15) level, secreted from AML cells, induces morphological remodelling of BMA and lipolytic pathway to generate fatty acid for tumour proliferation." (PMID 31334678, 2019). "Using tumor tissue or normal colon samples in the TCGA CRC dataset, we found no significant positive correlation between the gene expression level of GDF15 and age." (PMID 31389184, 2019).
tumor (continued). "GBM has been studied extensively for NT, GDF-15, S1P, and infection with CMV, which play important roles in tumor processes, in particular the viability, migration and invasion of tumor cells, GSC, angiogenesis, and tumor immune escape." (PMID 29467963, 2018). "Some of these genes, including GDF15, TGM2, VEGFA and ZNF385A were also up-regulated in primary tumor cells from patient 32 after co-culture with N-MSCs." (PMID 29503225, 2018). "Finally, growth/differentiation factor-15 (GDF-15), a TGF-beta family member, was expressed in response to liver injury and carcinogen exposure and was highly associated with stage, size, metastasis as well as inhibition of tumor growth and increased tumor invasiveness in gastrointestinal cancers." (PMID 25826080, 2016). "However, there are also reports suggesting that GDF-15 may act as a tumor suppressor." (PMID 26741507, 2016). "In conclusion, we showed that high induction of GDF15 following carboplatin treatment distinguishes platinum-sensitive from platinum-resistant tumor specimen, while high basal levels of GDF15 before treatment may serve as a marker for chemoresponse in these tumor models." (PMID 25490861, 2015). "Our research investigated the effects of GDF-15 on the maturation and function of DCs and reveals the possible role of GDF-15 in tumor immune escape." (PMID 24236027, 2013). "Although our researches clarified the effects of GDF-15 on the maturation and function of DCs and revealed a possible role for GDF-15 during tumor immune escape, the specific mechanism for these effects has not yet been elucidated." (PMID 24236027, 2013). "Enforced MIC-1/GDF15 overexpression in HCT-116 colon cancer cells, xenografted into nude mice, resulted in reduction in tumor size." (PMID 22952779, 2012). "In contrast, oncological factors such as TNM staging, tumor location, and histological subtype were not correlated with GDF15." (PMID 41016991, 2026). "It revealed that GDF15+ macrophages were enriched in ICB-sensitive OSCCs after treatment and might participate in mediating tumor regression." (PMID 41824793, 2026). "Similarly, growth differentiation factor 15 (GDF15) induces EMT-related gene expression in CRC cells and facilitates tumor invasion and dissemination." (PMID 41550840, 2026). "In contrast, GDF15 levels did not correlate with tumor location, histological subtype, or tumor progression." (PMID 41016991, 2026). "Interestingly, we found that quercetin, a phytochemical known for its anticancer properties via NAG-1/GDF15 modulation in various tumor types, influenced the pro-to-mature NAG-1/GDF15 ratio." (PMID 40316530, 2025). "Growth differentiation factor 15 (GDF15), a divergent member of the TGF-β superfamily, has emerged as a potential candidate biomarker because of its involvement in inflammation, cellular stress response, and tumor progression." (PMID 40725563, 2025). "Furthermore, GDF15 regulates chemosensitivity to oxaliplatin in CRC cells by reducing oxidative stress, which oxaliplatin exploits to induce tumor cell apoptosis." (PMID 40868185, 2025). "Second, GDF15 binds to its receptor GFRAL and activates a chronic inflammatory response via the PI3K/AKT/STAT3 pathway, which induces an imbalance in oxidative stress, resulting in increased tumor burden and drug resistance." (PMID 41035818, 2025). "This suggests that NAG-1/GDF15 could effectively neutralize growth factors and cytokines released from the tumor microenvironment." (PMID 40316530, 2025).